CTLA4 (cytotoxic T-lymphocyte associated protein 4)
Diseases named in the same sentence as CTLA4 in open-access papers (continued):
Sharing a sentence is not in itself a finding about the gene and the disease.
autoimmune disease (continued). "Furthermore, it is known that genetic polymorphisms of PD-1 and CTLA-4 are associated with various autoimmune diseases, such as thyroiditis, diabetes mellitus, and rheumatoid arthritis." (PMID 36765845, 2023). "Co-inhibition of PD-1 and LAG-3 may cause fewer adverse events than co-inhibition of PD-1 and CTLA-4, which is characterized by single-deficient autoimmune disease." (PMID 37179337, 2023). "It is worth noting that some alternatively spliced variants of T cell factors, such as IL2RA, IL7R, CD45, CD44, and CTLA-4, are associated with an increased risk of developing autoimmune diseases, such as multiple sclerosis, type 1 diabetes, and rheumatoid arthritis." (PMID 37895245, 2023). "Furthermore, LRBA deficiency leads to impaired trafficking of CTLA-4 on the Treg cells’ surface, causing disruption of immune homeostasis and leading to autoimmune disorders, organomegaly, and hypogammaglobulinemia." (PMID 36569874, 2022). "The non-synonymous mutations in CTLA4 gene might disturb its interaction with its ligands and can lead to autoimmune diseases and cancer." (PMID 36443461, 2022). "Furthermore, deficiency of genes encoding for IL-2, IL-2 receptor (CD25) or CTLA-4 are associated with autoimmune diseases, indicating that these Treg associated cytokines and molecules are important for the prevention of autoimmune disorders." (PMID 36173485, 2022). "Furthermore, the ITP cases were divided into primary ITP group without underlying disease and secondary ITP group caused by autoimmune disease to investigate their correlation with CTLA4 SNPs." (PMID 35459882, 2022). "The association of CTLA4 polymorphism has been established with various autoimmune diseases like rheumatoid arthritis, type 1 diabetes, and multiple sclerosis and also different cancers such as breast cancer, colorectal cancer, lung cancer, and cervical cancer." (PMID 36443461, 2022). "Furthermore, CTLA-4 SNPs, whose mRNA expression is decreased, are also significantly associated with the risk of autoimmune disease (i.e., Graves’ disease) development." (PMID 34584206, 2021). "The single nucleotide polymorphisms (SNP)s, rs3087243, rs231725, rs11571302, and rs11571297, located in the CTLA4-ICOS intergenic region were identified in predisposition to autoimmune diseases including rheumatoid arthritis, vitiligo, hypothyroidism, type 1 diabetes, and Graves’ disease by GWASs." (PMID 34736521, 2021). "Located on chromosome 2, CTLA4 gene polymorphisms might play an influential role in the development of autoimmune diseases and neoplasms." (PMID 33802937, 2021). "In a first search of cellular mechanisms relevant for (patho)physiological autoimmunity in general, and NMDAR1-AB in particular, we focused here on the gene encoding CTLA4, an Ig-superfamily member and dampener of T-cell activation, with recognized susceptibility to various autoimmune diseases." (PMID 32089545, 2021). "People whose CTLA4 checkpoint is blocked by antibody immunotherapy, or by germline mutations in the CTLA4 gene, often but not always develop severe gastrointestinal inflammatory disease and autoimmune diseases." (PMID 33113212, 2021). "The mAbs act through the inhibition of the CTLA-4 pathway, with a subsequent over-activation of T-lymphocytes that may predispose to the onset of autoimmune disease, as IIH." (PMID 34683167, 2021). "Previous studies have indicated that CTLA4 gene polymorphisms may be associated with the development of autoimmune diseases and cancers." (PMID 33802937, 2021). "Therefore, deficiency of CTLA-4 can be correlated with the development of autoimmune diseases such as multiple sclerosis." (PMID 34442365, 2021). "Its influence on CTLA-4 expression possibly determines the risk of autoimmune disease and cancers." (PMID 33802937, 2021). "Besides, the polymorphisms of CTLA-4 have already been proved to be candidates of the risk of the common autoimmune diseases at the genetic level." (PMID 34339393, 2021).
autoimmune disease (continued). "According to the literature genes encoding IL2RA (alpha subunit of Interleukin 2 receptor), IFIH1 (Interferon induced with helicase C domain 1) and CTLA-4 (cytotoxic T cell antigen 4) might be associated with autoimmune diseases pathogenesis." (PMID 32974248, 2020). "CTLA-4-deficient mice might develop large-scale lymphoproliferative diseases or spontaneous autoimmune diseases, and die in 4–5 weeks." (PMID 32210155, 2020). "The soluble form of CTLA-4 (sCTLA-4) is associated with several autoimmune diseases." (PMID 33272321, 2020). "Gene variants of the cytotoxic T-lymphocyte antigen 4 (CTLA4) gene, a negative regulator of T-cell response, have been associated with a predisposition to autoimmune diseases in different populations; however, the involvement of these genetic variants in the development of AA is controversial." (PMID 32278632, 2020). "Similar to our findings, both the PTPN22 rs2476601 and CTLA4 rs3087243 risk variants were shown to be susceptibility loci for autoimmune diseases including anti-neutrophil cytoplasmic antibody (ANCA)-associated vasculitis (AAV) and autoimmune polyglandular autoimmunity." (PMID 32328064, 2020). "Consequently, the CTLA-4 polymorphism has been reported to be associated with several autoimmune diseases." (PMID 33272321, 2020). "Moreover, there were several autoimmune diseases and cancers simultaneously associated with CTLA-4 and CD28 genes." (PMID 32210155, 2020). "CTLA4 is involved in the regulation of T-cell response during an immune reaction, and multiple CTLA4 single nucleotide polymorphisms (SNPs) have been associated with numerous autoimmune diseases, including RA." (PMID 32946523, 2020). "Our hypothesis that genetic variants associated with lower CTLA-4 expression levels and autoimmune disease susceptibility may be favorable during the course of sepsis is further supported by our findings for the H1: TAA haplotype." (PMID 30634576, 2019). "Mice deficient for a single inhibitory receptor (such as CTLA-4 or PD1) often display enhanced susceptibility to experimentally-induced autoimmune diseases or may spontaneously develop a lupus-like disease." (PMID 31824865, 2019). "The findings at the CTLA-4 rs3087243 position could be explained by observations that revealed lower CTLA-4 protein expression levels as well as higher susceptibility to autoimmune diseases in rs3087243 G allele carriers." (PMID 30634576, 2019). "Since heterozygous mutations of either CTLA4 or LRBA are sufficient to cause autoimmune diseases in humans, quantitative downregulation of CTLA-4 is sufficient to cause autoimmune diseases and thus provide a straightforward explanation for toxicity of clinical antibodies." (PMID 31267017, 2019). "Moreover, CTLA-4 gene single-nucleotide polymorphisms (SNPs) in humans were associated with autoimmune disorders." (PMID 31214024, 2019). "Many SNPs associated with autoimmune diseases have been identified for the CTLA-4 gene." (PMID 31177287, 2019). "Because the functional single-nucleotide polymorphism (SNP) rs231775 of the CTLA-4 gene is associated with autoimmune diseases and because of the critical role of the immune reaction in sepsis, we intended to examine the effect of this polymorphism on survival in patients with sepsis." (PMID 30310101, 2018). "The polymorphisms reducing the CTLA-4 expression or function may cause autoimmune clonal T cell proliferation and thus the development of autoimmune diseases." (PMID 29850619, 2018). "The CTLA4 gene on human chromosome 2q33 is one of the candidate genetic markers for autoimmune diseases, encodes a cell surface molecule that is expressed on the surface of activated T lymphocytes and has the most remarkable function of down regulation of the immune response." (PMID 26963610, 2016).
autoimmune disease (continued). "Although current methods of immunotherapy in cancer are largely based on the use of the immune checkpoint inhibitors anti-CTLA-4 and anti-PD-1 antibodies, the major obstacle resides in opportunistic autoimmune disorders and associated morbidity resulting from altered immune regulation." (PMID 27965674, 2016). "According to prior studies on the association the CTLA4 gene with the development of various autoimmune diseases, the exon 1 +49 A/G polymorphism in CTLA4 exon 1 has been reported to be involved in the development of autoimmune diseases including Graves’ disease and Hashimoto thyroiditis." (PMID 26963610, 2016). "Thus, given the critical role of CTLA-4 in immunologic homeostasis and the known irAE profile, patients with underlying autoimmune disease were usually excluded from clinical trials involving CTLA-4 blocking drugs." (PMID 26337719, 2015). "Notably, the expression of a tailless CTLA-4 molecule prevents lethal lymphoproliferation in CTLA-4-/- mice and mice with CTLA-4 mutated in its intracellular domain don’t develop autoimmune diseases." (PMID 26110267, 2015). "The inhibitory role of CTLA-4 in maintaining homeostasis of inflammatory and immune reactions makes it a potential candidate gene for determining the genetic predisposition of infectious and autoimmune diseases." (PMID 26108796, 2015). "The soluble form of CTLA-4 has been linked to autoimmune diseases." (PMID 25538704, 2014). "The CTLA-4 -1722T/C polymorphism (T→C) would reduce a transcription factor binding site for nuclear factor 1 and weaken the expression of cell surface CTLA-4, which might play an important role in cancer and autoimmune disease susceptibility." (PMID 24710335, 2014). "Polymorphisms of the CTLA-4 gene associated with autoimmune diseases could help in identifying interferon treatment benefits." (PMID 24475110, 2014). "Moreover, the relationship between CTLA-4 polymorphism(s) described associated with autoimmune diseases (including PBC) and the ability to produce the spliced soluble form of the molecule has been not yet elucidated." (PMID 25383768, 2014). "Negative signaling of CTLA-4 has an active role in the regulation of autoreactive T cells, and disturbance of the normal control of the CTLA-4 may cause the pathogenesis of autoimmune diseases." (PMID 25452756, 2014). "It is likely that defective CTLA-4 expression and function are associated with autoimmune diseases." (PMID 25452756, 2014). "Together these observations suggest that CTLA4 might play a critical role in regulating self-tolerance, and hence in susceptibility to autoimmune disease." (PMID 25003519, 2014). "CTLA-4-deficient mice have lymphoproliferative disorders and early fatal multi-organ tissue destruction, whereas PD-1-deficient mice spontaneously develop milder forms of autoimmune diseases." (PMID 23801991, 2013). "Theoretically, polymorphisms of CTLA4 that reduce CTLA-4 expression may cause autoimmune T-cell clonal proliferation, thus contributing to the pathogenesis of autoimmune diseases." (PMID 23970995, 2013). "Furthermore, there appear to be disease-specific genes, such as the gene encoding the TSHR in Graves' disease and a larger group of susceptibility genes, such as CTLA4, which are common to many autoimmune diseases." (PMID 22530160, 2012). "Finally, rs231779 near CTLA4 has been associated with many other autoimmune diseases as well as with autoimmune hypothyroidism in candidate gene studies." (PMID 22493691, 2012). "In addition to the HLA and CTLA4 gene loci, there are confirmed associations (2 or more reports) for a number of genes also common to many autoimmune diseases: PTPN22, CD40, IL2RA (CD25), and FCRL3." (PMID 22530160, 2012). "Moreover, single nucleotide polymorphisms (SNPs) with a point mutation in exon 1 of CTLA-4 gene have been linked to susceptibility to several autoimmune disease." (PMID 23049754, 2012).
autoimmune disease (continued). "Multiple polymorphisms within the CTLA-4 gene have been found to be associated with susceptibility to autoimmune diseases (e.g., the GG allele of the +49 AG polymorphism is associated with decreased expression of CTLA-4 upon T-cell activation and thus a higher proliferation of T-cells)." (PMID 21044351, 2010). "Recent studies also suggested that polymorphisms in the CTLA4 gene may influence the development of autoimmune diseases." (PMID 21637411, 2010). "In addition, genetic studies revealed that there is an association between CTLA-4 gene polymorphism and susceptibility to autoimmune diseases." (PMID 19570209, 2009). "In fact, sampling bias may account for some contradictory results previously reported for CTLA-4 association studies in autoimmune diseases." (PMID 17341301, 2007). "In fact, sampling bias may partly account for some contradictory results previously reported for CTLA-4 association studies in autoimmune diseases." (PMID 17341301, 2007). "Some reports imply that the distribution of certain alleles of the CTLA-4 gene in cancer is contrary to autoimmune diseases: that is, those alleles that confer susceptibility to autoimmunity are sparse in patients with cancer or associated with good prognosis of the cancer." (PMID 17825114, 2007). "Therefore, the functional basis for the genetic association between CTLA-4 and autoimmune diseases as well as the etiological mutation in the CTLA-4 region should be re-considered." (PMID 16259622, 2005). "This induced autoreactive repertoire is similar to those of patients with autoimmune diseases, and autoreactive B cells may induce the development of irAEs frequently associated with anti–CTLA-4 treatment by presenting self antigens through their MHC class II to T cells." (PMID 41026527, 2025). "Similarly, fatal autoimmune diseases develop in individuals with mutation of CD25, whereas individuals with heterologous mutations of CTLA-4, including CTLA-4 haploinsufficiency, may develop autoimmune diseases of different spectrums." (PMID 39000278, 2024). "Genetic susceptibility plays a crucial role in autoimmune disorders, and immune modification genes (such as human leukocyte antigen classes I and II) and sites related to cytotoxic T lymphocyte-associated protein 4 (CTLA-4) may be involved in the autoimmune process." (PMID 38505287, 2024). "Therefore, CTLA‐4 deficiency or mutation can lead to autoimmune diseases." (PMID 38883218, 2024). "Earlier reports suggested that PD-1 and CTLA-4 are associated with the suppressive functions of Treg cells, but a consensus is emerging that these inhibitory receptors can individually restrict Treg capacity and suppressive function during autoimmune disease, cancer and infection." (PMID 36960049, 2023). "Therefore, CTLA4 gene variants have been associated with several autoimmune diseases, such as autoimmune thyroid disease, Graves’ disease, Hashimoto’s thyroiditis, Type 1 diabetes, psoriasis, Behçet’s disease, and alopecia areata, although the latter remains controversial." (PMID 36163113, 2022). "As the autoimmune phenotype in Ctla4−/− mice occurs at a young age, and targeted mutation of the Ctla4 gene in adult mice leads to less severe autoimmune disease, we reasoned that mice may be most susceptible to anti-CTLA-4 mAbs if they are administrated at a young age." (PMID 29463898, 2018). "The cytotoxic T-lymphocyte antigen 4 (CTLA4) gene, residing in human chromosome 2q33, encodes a key negative regulator of T-cell activation and proliferation during the immune response and thereby may influence T-cell mediated autoimmune diseases such as GD." (PMID 29299173, 2017). "Therefore, further research on relation between various CTLA4 polymorphisms, dynamics of flCTLA4 versus sCTLA4 expression and their turnover in autoimmune hypothyroidism as well as other autoimmune diseases is needed to clarify the role of CTLA4 in the regulation of immune response." (PMID 26963610, 2016).
autoimmune disease (continued). "We also propose that an understanding of the molecular mechanisms underlying the autoimmune disease of patients who have generated significant responses to anti-CTLA-4 therapy could lead to the identification of novel combinatorial immunotherapy regimens with enhanced clinical efficacy." (PMID 25992290, 2015). "In conclusion, the sharing of a similar genetic background suggests that different autoimmune diseases may have similar pathogenic mechanisms, and the shared association with CTLA-4 and PTPN22 variants affects the threshold for activation or deactivation of autoreactive T cells." (PMID 25452756, 2014). "Given the critical role of CTLA-4 in maintaining immunologic homeostasis, clinical trials involving ipilimumab and cancer immunotherapies in general have excluded patients with underlying autoimmune diseases out of concern for triggering autoimmune exacerbations in these individuals." (PMID 25349698, 2014). "The gene of Cytotoxic T Lymphocyte-associated Antigen 4 (CTLA4), a negative regulator of T lymphocytes, contains a single-nucleotide polymorphism (SNP) at position +6230A->G (ct60A->G), which has been found associated with several autoimmune diseases and appears to reduce T-cell inhibitory activity." (PMID 19609446, 2009). "The FDA’s approval of CTLA-4, PD-1, and PD-L1 antibodies underscores the therapeutic potential of a deeper understanding of co-inhibitory pathways, with agonistic antibodies for autoimmune diseases showing promise." (PMID 40356928, 2025). "It is well known that genetic polymorphisms of CTLA4 and PDCD1 genes can increase the risk of developing autoimmune diseases, including IIHs." (PMID 41465179, 2025). "Several factors have been identified as predisposing to the development of irAEs, including a history of autoimmune disease, treatment with CTLA-4 inhibitors, and impaired renal function (grade ≥3)." (PMID 40406130, 2025). "Previous studies have shown that canine leukocyte/lymphocyte proliferation is suppressed by the addition of CTLA-4 Ig, highlighting its potential application as an immunosuppressant for transplantation and autoimmune disease treatment." (PMID 40463388, 2025). "Even though inhibitory checkpoint therapy is in clinical use for about a decade, the CTLA‐4 agonist Abatacept still is the only CIM activator on the market to treat autoimmune diseases." (PMID 39945070, 2025). "CTLA-4 plays an important role in peripheral tolerance and the prevention of autoimmune disease by inhibition of T cell activation." (PMID 40011465, 2025). "The induction of autoimmune disease has been reported for several other monoclonal antibodies, such as autoimmune colitis with CTLA4-specific antibodies or autoimmune thyroid disease in patients treated with alemtuzumab." (PMID 39796776, 2025). "CTLA-4 is a key regulator of immune homeostasis whose alterations have been observed in many autoimmune disorders." (PMID 40149457, 2025). "Elucidating the immunoregulatory mechanisms and functions of CTLA-4 in these conditions will facilitate the identification of effective immunotherapeutic targets for autoimmune diseases." (PMID 41357215, 2025). "The research combined terms for autoimmune diseases, ICIs (anti-CTLA-4, anti-PD-1/PD-L1), and cancer types, emphasizing studies reporting safety or efficacy outcomes." (PMID 41341585, 2025). "CTLA4 was the key stimulatory receptor during T cell activation, and CTLA4 modulated multiple autoimmune disease responses." (PMID 38604154, 2024). "CTLA-4 is involved in maintaining tolerance to autoimmune diseases, such as diabetes, as well as spontaneous abortion tendencies." (PMID 38807592, 2024). "Genetic ablation of CTLA-4 in mice has been shown to result in multi-organ toxicity and lethal phenotype, while administration of pan-CTLA-4 antibody to naive mice can lead to spontaneous development of autoimmune diseases." (PMID 38053333, 2024).